ALK (ALK receptor tyrosine kinase)
Diseases named in the same sentence as ALK in open-access papers (continued):
Sharing a sentence is not in itself a finding about the gene and the disease.
lung adenocarcinoma (continued). "In summary, using the Ventana (D5F3) IHC, we found the homogeneity of ALK expression in lung adenocarcinoma samples and concordance in ALK status between primary tumours and corresponding lymph node metastases." (PMID 28887531, 2017). "Molecularly targeted therapies improve outcome for lung adenocarcinoma patients whose tumors harbor mutant EGFR or translocated ALK, RET or ROS1, with an encouraging response for those with mutated BRAF, MET, NTRK-1 & 2 and ERBB2." (PMID 27998968, 2017). "Although anaplastic lymphoma kinase (ALK) fusion genes are generally identified in lung adenocarcinoma patients, they are relatively rare in patients with squamous cell carcinoma (SqCC)." (PMID 28683775, 2017). "Alectinib, a second-generation anaplastic lymphoma kinase (ALK) inhibitor, is a key drug for ALK rearranged lung adenocarcinoma." (PMID 29207989, 2017). "Metastatic ALK-rearranged lung adenocarcinoma patients treated with ALK inhibitors demonstrate higher response rates, improved progression-free survival, and reduced toxicity relative to those treated with conventional chemotherapy regimens." (PMID 28683775, 2017). "ALK rearrangement was an adverse prognostic factor in surgically-resected, early-stage lung adenocarcinoma patients." (PMID 29156778, 2017). "A total of 13 patients out of a cohort of 212 patients with lung adenocarcinoma, presented ALK rearrangements (6%) confirmed by tumor biopsy." (PMID 28938646, 2017). "Identification of EML4-ALK fusion genes in lung adenocarcinoma has led to the application of ALK inhibitors for the treatment of lung adenocarcinoma with EML4-ALK fusions." (PMID 28636652, 2017). "Among the alterations, rearrangement of the anaplastic lymphoma kinase (ALK) gene and echinoderm microtubule-associated protein-like 4 (EML4) occurs in approximately 5% of lung adenocarcinomas, representing the most frequent rearrangements." (PMID 28970558, 2017). "Patient 1 was a 57-year-old male with an ALK-rearranged Stage IV lung adenocarcinoma who was administered alectinib as first-line therapy." (PMID 29207989, 2017). "In comparison, a study from European Thoracic Oncology Platform Lungscape Project found that ALK-positivity was related to an improved overall survival in early-stage lung adenocarcinoma patients." (PMID 29156778, 2017). "Of the 89 lung adenocarcinoma patients, 72 underwent testing for epidermal growth factor receptor (EGFR) mutation and anaplastic lymphoma kinase (ALK) rearrangement." (PMID 29156821, 2017). "Patient 2 was a 64-year-old woman with an ALK-positive lung adenocarcinoma who was administered alectinib as third-line therapy." (PMID 29207989, 2017). "ALK rearrangement was an adverse prognostic factor in surgically-resected lung adenocarcinoma patients." (PMID 29156778, 2017). "Previous studies have demonstrated the intratumour heterogeneity of ALK gene translocation in lung adenocarcinoma samples." (PMID 28887531, 2017). "Rearrangements in the anaplastic lymphoma kinase (ALK) gene have been found in 3%–7% lung adenocarcinomas." (PMID 28938595, 2017). "In lung adenocarcinoma, rearranged genes, including ALK, ROS1, RET, NTRK1, and NRG1, have been reported." (PMID 28894699, 2017). "Here, we found a greater proportion of KRAS mutation subgroup showed the higher expression of PD-L1, compared with that of EGFR/ALK/KRAS wild-type subgroup in lung adenocarcinoma patients." (PMID 28451792, 2017). "ALK status was homogeneous in lung adenocarcinoma samples and was generally stable during metastasis." (PMID 28887531, 2017). "For example, in lung adenocarcinoma, EGFR testing for mutations and ALK rearrangements allows for precision therapy with targeted kinase inhibitors, such as gefitinib for EGFR and Crizotinib for ALK fusion." (PMID 29068423, 2017). "ALK fusion genes are typically identified in approximately 5.0% of patients with lung adenocarcinoma, although they are rare in patients with squamous cell carcinoma (SqCC)." (PMID 28683775, 2017).
lung adenocarcinoma (continued). "We herein report a case of surgically resected lung adenocarcinoma that presented as a cavitary mass harboring ALK fusion with rare radiological features." (PMID 28321808, 2017). "Some specific histological features have been reported in lung adenocarcinomas with ALK or ROS1 fusions, such as a mucinous cribriform pattern or solid growth pattern with signet ring cells." (PMID 29163763, 2017). "Signet-ring cells are a rare feature of primary lung adenocarcinoma; the presence of signet-ring-cell elements is significantly more frequent in ALK+ lung cancer." (PMID 28321808, 2017). "In the present study, we reported the feasibility of the NanoString ALK fusion panel to detect the ALK fusion transcripts in formalin-fixed paraffin-embedded (FFPE) samples of lung adenocarcinoma in a Brazilian population." (PMID 28549458, 2017). "With the discovery of epidermal growth factor receptor (EGFR) mutations, anaplastic lymphoma kinase (ALK) rearrangements, and effective targeted therapies, therapeutic options are expanding for patients with lung adenocarcinoma." (PMID 27200298, 2016). "For example, several studies have suggested that ALK-rearranged lung adenocarcinomas were most likely to be observed in the cases with signet-ring cells." (PMID 27708233, 2016). "Among the three groups, we evaluated only patients with stage IIIB–IV lung adenocarcinoma who had EGFR mutations (n = 126), KRAS mutations (n = 35), or ALK rearrangements (n = 47) to avoid the influence of confounding factors such as tissue type and staging." (PMID 27518729, 2016). "In conclusion, we reported significant discrepancies of ALK status in lung adenocarcinoma subtypes according to the IALSC/ATS/ERS classification in Chinese patients." (PMID 27386342, 2016). "Some Food and Drug Administration (FDA) approved drugs for stage IV lung adenocarcinoma target molecular alterations including mutations in epidermal growth factor receptor (EGFR) and rearrangements of anaplastic lymphoma kinase (ALK)." (PMID 27220886, 2016). "Among the 24 advanced lung adenocarcinoma patients with known ALK rearrangements confirmed by their tissue biopsies, ALK rearrangements were successfully detected from plasma samples of 19 patients with 79.2% sensitivity and 100% specificity." (PMID 27564104, 2016). "The study assessing molecular characteristics of lung adenocarcinomas, which harbor EGFR, KRAS mutations or ALK rearrangements as well as triple negative adenocarcinomas, dominated the top 10 alignment outcomes." (PMID 26967245, 2016). "The second most important altered TKR in lung adenocarcinoma, ALK (Anaplastic Lymphoma Kinase), is a transmembrane TKR integrated in the insulin receptor superfamily." (PMID 27528792, 2016). "In summary, taken the data of both specimens into account, we diagnosed an ALK-positive lung adenocarcinoma rendering the patient eligible to crizotinib." (PMID 27863497, 2016). "Detecting ALK rearrangement is emerging as an important component of the pathologic analysis of lung adenocarcinomas." (PMID 27386342, 2016). "We have also previously reported that the main tumor in early-stage ALK-positive lung adenocarcinoma is typically solid, with few GGO components and a low tumor disappearance rate." (PMID 27518729, 2016). "A total of 268 lung adenocarcinoma patients were screened for ALK expression by IHC using the anti-ALK antibody D5F3 clone." (PMID 27142166, 2016). "A reclassification of 2299 surgically resected lung adenocarcinomas was performed, and ALK status was detected by immunohistochemistry (Ventana Medical Systems) in Shanghai Chest Hospital." (PMID 27386342, 2016). "We reported significant discrepancies of ALK status in lung adenocarcinoma subtypes in Chinese patients." (PMID 27386342, 2016).
lung adenocarcinoma (continued). "The emergence of targeted therapy such as EGFR inhibitors and anaplastic lymphoma kinase (ALK) inhibitors have significantly changed the treatment strategy against lung adenocarcinoma AC, leading to marked improvements in patient survival." (PMID 26936993, 2016). "Although we did not evaluate these specific characteristics in the present study, our results confirm that ALK-positive lung adenocarcinomas are typically solid, even at the advanced stage, which is likely due to their distinct pathological states." (PMID 27518729, 2016). "The most representative examples are gefitinib/erlotinib and crizotinib for lung adenocarcinomas harboring EGFR mutations and ALK/ROS1 fusion, respectively." (PMID 27223439, 2016). "In summary, the 6 FISH-negative and Ventana IHC-positive ALK lung adenocarcinoma cases who were treated with crizotinib responded well to the drug, with similar objective response and disease control rates to those previously reported." (PMID 27418132, 2016). "Patients with ALK-positive lung adenocarcinoma tended to present with lymphadenopathy, extranodal invasion, and lymphangitis." (PMID 27518729, 2016). "The US Food and Drug Administration (FDA) has approved crizotinib to treat locally advanced or metastatic ALK rearrangements lung adenocarcinomas." (PMID 27386342, 2016). "Among the three groups, we evaluated only patients with stage IIIB–IV lung adenocarcinoma who had EGFR mutations (n = 126), KRAS mutations (n = 35), or ALK rearrangements (n = 47)." (PMID 27518729, 2016). "Currently, however, there is only limited evidence of the efficacy and tolerability of crizotinib in Chinese patients with ALK‐positive lung adenocarcinoma." (PMID 26880708, 2016). "ALK gene rearrangement, which is another targetable genetic change in lung adenocarcinomas, was discovered in 2007." (PMID 27655296, 2016). "In our series, signet-ring cells presented only in two cases (2/12), which seems lower in previous reports with surgical cases (33-55%), and much lower than ALK-rearranged lung adenocarcinoma (71%)." (PMID 27708233, 2016). "So, we think that the ALK IHC (D5F3) assay is sensitive in the use of ALK test in lung adenocarcinoma." (PMID 27472693, 2016). "This study aimed to determine the relationship between ALK status and lung adenocarcinoma subtypes, according to the IALSC/ATS/ERS classification in Chinese patients." (PMID 27386342, 2016). "A 50-year old man diagnosed with stage IV lung adenocarcinoma presented with MPE and an ALK fusion gene mutation." (PMID 28018791, 2016). "In the present study, we found a higher ORR and significant PFS benefit of first‐line crizotinib versus standard chemotherapy in ALK‐positive Chinese lung adenocarcinoma patients, which was consistent with previous reports." (PMID 26880708, 2016). "Approximately 3–6 % of lung adenocarcinoma were shown to harbor rearrangements of the ALK gene, which has been demonstrated to be a potent oncogenic driver and a promising therapeutic target." (PMID 27386342, 2016). "The frequency of these driver mutations were identical to the previous report that analyzed unselected Japanese lung adenocarcinoma patients; EGFR mutation, KRAS mutation, ALK fusion, or HER2 mutation were identified in 67.7% (216/319)." (PMID 27100677, 2016). "The findings of this study suggest that first‐line crizotinib treatment resulted in significantly higher response rates and a longer PFS in comparison with first‐line standard chemotherapy in Chinese patients with ALK‐positive, advanced lung adenocarcinoma." (PMID 26880708, 2016). "In conclusion, there was a significant PFS benefit of first‐line crizotinib versus first‐line standard chemotherapy among Chinese patients with ALK‐positive lung adenocarcinoma." (PMID 26880708, 2016).
lung adenocarcinoma (continued). "This study was mainly conducted to compare the PFS of Chinese patients with ALK‐positive lung adenocarcinoma who received first‐line crizotinib therapy with that of patients who received first‐line standard chemotherapy." (PMID 26880708, 2016). "Of particular importance, the system reported similar expression patterns for primary tumor samples from patients with lung adenocarcinoma (positions 1-10) with ranking attributed to the mutation pattern either in EGFR, KRAS, or ALK genes." (PMID 26967245, 2016). "EML4-ALK-positive lung adenocarcinoma cell lines H3122 and H2228 were sensitive to ALK inhibitors crizotinib and NMS-E628." (PMID 27078848, 2016). "A 45-year-old female was diagnosed as having lung adenocarcinoma harboring an anaplastic lymphoma kinase (ALK) rearrangement, stage IV (T2bN3M1b)." (PMID 25889062, 2015). "IHC can be an alternative to FISH and using the highly sensitive detection methods in combination with high affinity antibodies, IHC can effectively detect ALK fusion protein in lung adenocarcinoma with high sensitivity and specificity." (PMID 25789627, 2015). "The rearrangement of the anaplastic lymphoma kinase (ALK) gene and echinoderm microtubule-associated protein-like 4 (EML4) gene occurs in approximately 5% of lung adenocarcinomas, leading to the overexpression of anaplastic lymphoma kinase." (PMID 25785456, 2015). "In the present study, we reported one case of ALK-positive lung adenocarcinoma with bone marrow matastasis given crizotinib treatment, the safety and efficacy was summarized." (PMID 25676401, 2015). "Six lung adenocarcinoma cell lines, with KRAS, EGFR, or ALK driver mutations were evaluated for Debio 1143 dose-dependent growth inhibition to identify optimal concentrations for use in combination assays." (PMID 26485762, 2015). "This method showed high sensitivity and specificity of 100% and 98% respectively, for detecting ALK rearrangement in primary lung adenocarcinoma." (PMID 26678488, 2015). "Now, oncogenic protein kinases inhibitors have been prevailing in lung adenocarcinoma, such as targeting epidermal growth factor receptor (EGFR) mutation or anaplastic lymphoma kinase (ALK) rearrangement." (PMID 26788508, 2015). "The driver genes involved in lung adenocarcinoma include KRAS, EGFR, ALK, and BRAF, and those implicated in lung squamous cell carcinoma (LSCC) include PIK3CA, FGFR1, EGFR, PDGFRA, and DDR2." (PMID 26373952, 2015). "Lung adenocarcinomas have shown more driver mutations that can be successfully targeted such as EGFR, ALK, ROS1." (PMID 26371045, 2015). "The rearrangement of the anaplastic lymphoma kinase (ALK) gene accounts for approximately 1%–6% of lung adenocarcinoma cases and defines a molecular subgroup of tumors characterized by clinical sensitivity to ALK inhibitors such as crizotinib." (PMID 26253541, 2015). "RFS of lung adenocarcinoma patients harboring EGFR mutations, KRAS mutations or ALK fusions were compared to that of wild-type patients." (PMID 26486077, 2015). "In this study, the incidence of ALK rearrangements in pleural effusion cells of lung adenocarcinoma was low (4.5%) according to the RT-PCR results." (PMID 25785456, 2015). "The ALK rearrangements were screened in this study in a large randomly selected cohort of patients with lung adenocarcinoma by FISH, IHC, and RT-PCR." (PMID 24992725, 2014). "In an era of targeted therapy, the status of EGFR and ALK should be identified in patients with lung adenocarcinoma before treatment." (PMID 24992725, 2014). "Later on additional fusion partners of ALK were identified with reports of variable expression of ALK in adenocarcinomas of the lung, neuroblastomas, breast, and esophageal cancers." (PMID 25054154, 2014). "Further studies on the correlation between radiological appearance and the clinical features of advanced ALK-rearranged lung adenocarcinoma are warranted." (PMID 24403104, 2014).
lung adenocarcinoma (continued). "According to specific oncogenic driver mutations, lung adenocarcinoma is divided to molecular subtypes such as EGFR, KRAS, ALK, HER2, BRAF and so on." (PMID 25198510, 2014). "In the present study, it was demonstrated that IHC with ALK monoclonal antibody D5F3 was useful for screening lung adenocarcinoma harboring ALK rearrangement." (PMID 25295103, 2014). "Right detection of anaplastic lymphoma kinase (ALK) gene rearrangement is pivotal to selection of patients with lung adenocarcinoma for ALK-targeted therapy." (PMID 24667320, 2014). "In recent years, rearrangements of the anaplastic large cell kinase (ALK) gene have been discovered in approximately 5% of lung adenocarcinomas, resulting in the constitutive expression of a fusion protein - most commonly EML4-ALK - with oncogenic activity." (PMID 24422905, 2014). "This assumption is consistent with the histological analysis of ALK-positive adenocarcinomas showing lower frequencies of lepidic growth and AAH/BAC (AIS) in the background of ALK-positive lung adenocarcinomas." (PMID 24885886, 2014). "In conclusion, the ALK rearrangement was studied in a large unselected sample collection of lung adenocarcinoma." (PMID 24992725, 2014). "Manually semiquantitative ALK IHC (primary antibody D5F3 coupled with secondary DAKO Envision system) used as the initial screening combined with auxiliary FISH confirmation is a reliable, economical approach to identify ALK positive lung adenocarcinoma." (PMID 24667320, 2014). "ALK rearrangements and driver mutations such as EGFR and K-ras are frequently found in all types of lung adenocarcinoma." (PMID 24885886, 2014). "The ALK rearrangement was detected in 430 specimens from individual patients with primary lung adenocarcinoma using FISH and Ventana IHC based on tissue microarrays." (PMID 24992725, 2014). "According to the final result of FISH analysis, 36 out of the 286 lung adenocarcinoma cases were identified with ALK+." (PMID 24422905, 2014). "In this study of the 368 lung adenocarcinoma collection, we observed good correlations between cases assigned ALK IHC scores 3+ and ALK positivity, as well as ALK IHC 1+/0 and ALK negativity." (PMID 24667320, 2014). "Despite significant progress in therapy of lung adenocarcinoma, all patients with EGFR mutations and ALK or ROS1 translocations receiving specific tyrosine kinase inhibitors will ultimately experience relapse." (PMID 24879454, 2014). "Common mutations in lung adenocarcinoma include K-RAS, EGFR, as well as translocations of the Anaplastic Lymphoma Kinase (ALK) gene." (PMID 25019058, 2014). "In this study, the ALK rearrangements in patients with primary lung adenocarcinoma were investigated, and results obtained through FISH, Ventana IHC, and RT-PCR were compared." (PMID 24992725, 2014). "Consistent with previous studies, we detected EML4–ALK fusions in ~1% (5/513) of lung adenocarcinoma samples, multiple ALK fusions, including a single STRN–ALK fusion, in thyroid cancer (3/498) and one in papillary renal carcinoma." (PMID 25204415, 2014). "ALK gene translocations have been previously detected in patients with lung adenocarcinoma and light or non smoking history." (PMID 24885608, 2014). "A considerable proportion of lung adenocarcinomas develop through acquisition of mutations in EGFR, KRAS, or ALK genes." (PMID 24466154, 2014). "Identification of the relationship between CT imaging findings and ALK molecular status can help define categories of lung adenocarcinoma that have distinct clinical, radiological, molecular, and pathological characteristics." (PMID 24403104, 2014). "In this study, we applied IHC analysis using CST’s D5F3 antibody to detect ALK rearrangement in a Chinese lung adenocarcinoma patient cohort to assess the sensitivity and specificity of IHC analysis." (PMID 24422905, 2014). "In conclusion, we identified 44 ALK-rearranged lung adenocarcinomas, the largest reports in China to date." (PMID 23922677, 2013).